IGF1 (insulin like growth factor 1)
Diseases named in the same sentence as IGF1 in open-access papers (continued):
Sharing a sentence is not in itself a finding about the gene and the disease.
Obesity (continued). "Since hyperinsulinemia suppresses growth hormone release, the sustained elevation in insulin levels during exercise may have contributed to the overall lower growth hormone and consequently IGF‐1 response we observed in the participants with obesity." (PMID 40574473, 2025). "We hypothesized that individuals with obesity would exhibit an attenuated increase in circulating IGF‐1 levels in response to acute endurance exercise, with levels returning to baseline immediately after the cessation of exercise." (PMID 40574473, 2025). "We conclude that humans with obesity have blunted serum total IGF‐1 response during exercise." (PMID 40574473, 2025). "Previous studies have reported that growth hormone secretion is reduced in children with obesity while IGF-1 is typically mildly increased, and IGF-1 may be one factor involved in the accelerated growth of pre-pubertal children with obesity." (PMID 39899498, 2025). "Third, diminished muscle quantity and quality in sarcopenic obesity reduces secretion of beneficial myokines including irisin, interleukin-15, and insulin-like growth factor-1, which ordinarily provide cardioprotection through local and systemic signaling mechanisms." (PMID 41463092, 2025). "Additionally, the accumulation of adipose tissue in obesity is thought to increase the production of various endogenous hormones such as sex steroids, insulin, and insulin-like growth factor-1." (PMID 41016748, 2025). "This study provides comprehensive evidence supporting the efficacy of CUDC-907 in EC, demonstrating its ability to inhibit tumor growth, restore PR expression, suppress the PI3K/Akt pathway, and reduce serum IGF-1 levels, particularly in obesity-driven disease models." (PMID 41262902, 2025). "However, this reduction is accompanied by a similarly decreased response in circulating IGFBP‐3, resulting in stable levels of free (biologically active) IGF‐1 in the circulation during exercise in humans with obesity." (PMID 40574473, 2025). "Other lines of evidence indicate that dysregulation of the IGF‐1 system may represent an additional mechanism linking obesity with BRCA mutant carriers." (PMID 40523654, 2025). "Circulating total IGF‐1 response to acute endurance exercise is impaired in obesity." (PMID 40574473, 2025). "Given the strong metabolic effects of IGF1 and the established links between its signaling components in conditions like obesity and diabetes, disrupted IGF1 signaling may also contribute to the development of obesity-related comorbidities." (PMID 40105689, 2025). "Several factors may explain this: men with obesity frequently have elevated serum levels of insulin, IGF-1, and leptin, with reduced adiponectin levels—all of which have been associated with prostate cancer in some studies." (PMID 40002302, 2025). "During puberty, the secretion of growth hormone, insulin-like growth factor 1 (IGF-1), and androgens increase physiologically, which may be caused by various factors, such as obesity, genetic factors, environmental stress, and chronic sleep deprivation." (PMID 41003387, 2025). "In women with obesity and type 2 diabetes, insulin and leptin levels are elevated, creating a hormonal environment that can promote cancer cell growth by promoting the activation of insulin-like growth factor 1 (IGF-1)." (PMID 40431387, 2025). "In obesity, altered IGF-1/IGFBP levels may impair IGF-1R-IRS/PI3K signaling in mammary tissue, compromising the production of milk." (PMID 40868103, 2025). "Notably, recent population studies have shown that IGF-1 levels are lower when individuals suffer from conditions such as obesity, lipid metabolism disorders, hypertension, and metabolic syndrome." (PMID 40538800, 2025). "The aim of this study was to investigate the relationship of insulin-like growth factor-1 (IGF-1) and mild subclinical hypothyroidism (MSH) in obese boys and to assess whether the presence of MSH exacerbates cardiovascular risk factors in obesity." (PMID 40379763, 2025).
Obesity (continued). "In addition, metabolic dysregulation and obesity appear to amplify IGF-1-mediated oncogenic effects." (PMID 41157306, 2025). "This IGF1 resistance may, in turn, contribute to the development of obesity and its related comorbidities." (PMID 40105689, 2025). "Despite obesity being associated with reduced basal and stimulated growth hormone secretion by the pituitary gland, circulating IGF‐1 levels are not always similarly reduced." (PMID 40574473, 2025). "On the other hand, hyperinsulinemia may foster the potential of (mitogenic) mitogen-activated protein (MAP) kinase-related signaling, which can also occur via IGF1 receptors due to increased free insulin-like growth factor-1 (IGF1) levels in obesity." (PMID 40277890, 2025). "In contrast to what occurs in the population with obesity, where IGF-1 levels tend to be low, a positive correlation between body mass index (BMI) and IGF-1 levels has been reported in patients with acromegaly, indicating that the higher the disease activity, the higher the BMI value." (PMID 40142714, 2025). "Additionally, obesity alters leptin and insulin-like growth factor 1 (IGF-1) concentrations, influencing LH signaling to the gonads and, possibly, ovarian function." (PMID 40711323, 2025). "This underscores the complex interplay between obesity, diabetes, and IGF-1 levels." (PMID 39578883, 2024). "Thus, these mice revealed a novel regulatory mechanism that links energy status to the development of obesity through the control of IGF1 secretion and PPARγ signaling." (PMID 39136185, 2024). "Moreover, we found that, after dividing the patients by weight, IGF-1 increased significantly only in subjects with overweight and obesity." (PMID 38902646, 2024). "Both circulating insulin and IGF-1 are increased in obesity." (PMID 39201522, 2024). "Obesity typically leads to changes in the IGF system, resulting in lower IGF-1 availability." (PMID 38737552, 2024). "Despite this, a recent systematic review has analyzed the relationship among IGF-1, growth hormone, and obesity, highlighting that a modulation of these hormones could prevent the progression of metabolic syndrome and associated cardiovascular complications." (PMID 38920551, 2024). "Elevated anti-inflammatory cytokines (IL-4 and IL-10) and neurotrophic factors (BDNF, IGF-1) in silymarin-treated mice suggest that silymarin may offer neuroprotective benefits by mitigating obesity-related neuroinflammation." (PMID 39624169, 2024). "It has been reported that obesity suppresses IGF‐1/AKT signaling owing to increased pro‐inflammatory cytokines and toxic lipid metabolites and increases muscle atrophy by allowing phosphorylated Smads to enter the nucleus and regulate MuRF1 and Atrogin1 transcription and active UPS." (PMID 39055231, 2024). "Additionally, increased levels of circulating insulin and insulin-like growth factor 1 (IGF1), typically associated with high BMI and obesity, positively influence aromatase activity in the adipose tissue." (PMID 39253073, 2024). "Children with obesity had significantly lower IGF-1 values than those with other BMI categories." (PMID 39438878, 2024). "The main findings of this retrospective study were that individuals identified as dGHD had lower IGF-1 concentrations at baseline, with a higher increase after 1 year of treatment, and had a higher prevalence of pathological retesting and overweight/obesity at the end of treatment." (PMID 38495788, 2024). "Also, girls with abnormal anthropometric measures, particularly those with short stature and those with overweight or obesity, had substantially higher IGF-1 levels than boys with similar nutritional status." (PMID 39438878, 2024). "For instance, while leptin may directly enhance cell migration, its impact could be modulated by other factors such as IL-6 or IGF-1, which are also upregulated in obesity." (PMID 39339753, 2024).
Obesity (continued). "Ghrelin, a polypeptide with cardioprotective properties, has been observed to target the lncRNA H19/miR‐29a/insulin‐like growth factor 1 (IGF‐1) signaling pathway and the lncRNA HOTAIR/miR‐196b/IGF‐1 signaling pathway, thereby mitigating cardiomyocyte injury associated with obesity." (PMID 38405061, 2024). "The exact mechanism for the drop in IGF-1 levels during puberty remains unclear; however, it is hypothesized that low testosterone levels in boys with obesity may be a contributing factor, although this hypothesis does not seem to apply to girls." (PMID 38398863, 2024). "Previous studies observed similarly lower levels of IGF-1 in children with obesity." (PMID 39438878, 2024). "Exercise may induce positive effects on improvements in body composition and physical fitness, as well as on blood levels of metabolic biochemicals such as C-peptide and IGF-1, in adolescent boys with obesity." (PMID 39822775, 2024). "It is known that IGF1 plays a key role in obesity-related endocrine cancers such as BC." (PMID 38612922, 2024). "Nevertheless, the observed correlations of serum IGF1 with gender, LN metastasis, and tumor stage in non-obese CRC patients spotlight the role of the IGF system in risk stratification and pathology of obesity-CRC association." (PMID 38704452, 2024). "Moreover, this study is novel in demonstrating the promising roles of blood levels of C-peptide and IGF-1 in contributing to exercise-induced improvements in body composition and physical fitness in early adolescent boys with obesity." (PMID 39822775, 2024). "Therefore, the present study examined the effects of a 16-week EP, including CRAE, on body composition, physical fitness levels, and circulating hormones, including C-peptide, resistin, IGF-1, and growth hormone (GH), in adolescent boys with obesity." (PMID 39822775, 2024). "Moreover, in a preliminary analysis with a machine learning approach, our group found that IGF-1 plays a crucial role in the pathogenesis of the metabolic derangement observed in many patients with obesity." (PMID 36851702, 2023). "Among these factors, IGF-1 plays an important role in obesity-related endocrine cancers." (PMID 36755926, 2023). "Additionally, we summarize the current evidence regarding the efficacy and safety of GH and IGF-1 as therapeutic targets for managing obesity, including in pharmacological interventions and hormone replacement therapy." (PMID 37298507, 2023). "At present, most studies suggest that hyperglycemia, hyperinsulinemia, IGF-1, DNA damage, inflammatory factors, and obesity may be involved in the pathologic process of diabetes related tumors." (PMID 37335291, 2023). "This suggests that the increase in IGF-1 is specific to diet-induced obesity and may be contributing to the development of myeloma." (PMID 36909335, 2023). "Several hormones released by adipose tissue may influence linear growth in the context of obesity, both through the growth hormone insulin-like growth factor-1 (IGF-1) axis and directly through the epiphyseal growth plate." (PMID 38034825, 2023). "Given its diverse biological functions, any defects in IGF1 may lead to IR, obesity, and inflammation which are involved in NAFLD etiology." (PMID 37948568, 2023). "A more recent study demonstrated that obesity also induces stress granule formation via IGF1/PI3K/S6K1 signaling in orthotopic PDAC transplant models and that inhibition of stress granule formation at multiple nodes along this pathway impedes obesity-driven tumor growth in vivo." (PMID 37648285, 2023). "Apart from obesity increasing insulin, IGF-1, leptin, IL-6, TNF-α and decreasing levels of adiponectin which activates the PI3K-AKT signalling pathway in CRC, high BMI inhibits methylation of PI3K-AKT signalling pathway genes, constitutively activating the pathway." (PMID 37233716, 2023).
Obesity (continued). "It has been reported that high milk intake, but not meat intake, increased the concentrations of IGF-1 and was associated with increased overweight and obesity later during childhood." (PMID 37614409, 2023). "It is tempting to speculate that the clinical severity of SARS-CoV-2 infections may be related to the interplay among ferritin metabolism, obesity, hepatic steatosis, and the GH/IGF-1 axis." (PMID 36851702, 2023). "Clinical trials have investigated the potential use of GH and IGF-1 as interventions for obesity." (PMID 37298507, 2023). "Evidence suggests that GH and IGF-1 could contribute to the onset of obesity by impacting inflammation and oxidative stress." (PMID 37298507, 2023). "High levels of insulin-like growth factor 1 (IGF1) and insulin in obesity downregulate Glycogen synthase kinase 3 beta (GSK3B) activity by phosphorylating its serine residue, thereby altering the IL-17 signaling pathway, including upregulation of CXCL1, CCL20, and IL-6 expression." (PMID 37680632, 2023). "Thus, obesity as well as metabolic syndrome are risk factors for both prostate cancer as well as CRC, and both are linked to high IGF-1 levels, which in turn is associated with an increased risk of both prostate cancer and CRC." (PMID 37341814, 2023). "Another possible hypothesis suggests that obesity contributes to the increased circulating insulin and insulin-like growth factor 1 (IGF-1), which, in turn, can promote cell proliferation and tumor growth." (PMID 38068818, 2023). "Serum IGF‐1 was measured as part of the routine tests for overweight/obesity." (PMID 38053473, 2023). "Low IGF-1 levels are observed in obesity-induced liver dysfunction." (PMID 36991247, 2023). "Increased diet-induced IGF-1 and insulin levels, which are observed in obesity in Western countries, may lead to the increased proliferation and inhibition of apoptosis of CSCs via PI3K/AKT/Wnt signaling." (PMID 36835075, 2023). "In obesity, both IGF1 concentrations and vitamin D status are reduced; yet, for both variables, associations have been seen between lower concentrations and high blood pressure, disturbed glucose metabolism, cardiovascular disease, and adverse lipid profiles, regardless of body mass." (PMID 37892272, 2023). "Therefore, previous studies suggest an association between IGF-1 and IGF-1R and BC risk in women with obesity." (PMID 37512149, 2023). "Another hypothesis states that obesity results in elevated levels of insulin and insulin-like growth factor 1 (IGF-1), a known mitogen." (PMID 37629396, 2023). "Therefore, the IGF-1 level has certain clinical predictive value in diseases such as dwarfism, cardiovascular disease, cerebrovascular disease, obesity, and type 2 diabetes." (PMID 37266131, 2023). "This is in line with several studies showing that obesity-related host signaling, including Insulin-like Growth Factor 1 (IGF-1), Epidermal Growth Factor (EGF) and IL pathways, may impact on CEBP-β expression and activity." (PMID 37447165, 2023). "Moreover, the specific relationship between IGF-1′s mechanism and estrogen-mediated pathways was greatly enhanced in postmenopausal women with obesity." (PMID 37512149, 2023). "Therefore, while GH and IGF-1 show promise as therapeutic agents for obesity, more research is needed to fully understand their effects and potential side effects." (PMID 37298507, 2023). "Plasma IGF-1 is predominantly inactive and slightly related to obesity and hypertension in humans." (PMID 37623843, 2023). "GH and IGF-1 are generally reduced in obesity and play a significant role in insulin sensitivity." (PMID 36831184, 2023). "Indeed, the PI3K-AKT signaling pathway, a well-known regulator of cancer metabolism, is regulated by several growth factors, such as insulin, IGF-1, and leptin, whose levels are modified in obesity." (PMID 35158830, 2022).
Obesity (continued). "However, gECs showed increased expression of Fos, Fosb and Egr1 and increased expression of FGF receptor, nerve growth factor and IGF1 signaling networks in obesity." (PMID 36400935, 2022). "Despite their obesity, we found increased levels of growth hormone (GH) mRNA and protein in the pituitary, as well as increased insulin-like growth factor 1 (IGF-1) protein levels in the liver and plasma of Sim1-cre;mir-7fl/fl mice compared to mir-7fl/fl controls." (PMID 36175420, 2022). "The NEAT1-hsa-miR-204-5p-IGF1 axis may serve as a target for estradiol-leptin synergy in the uterine tissue of patients with obesity and as a biomarker to predict disease." (PMID 36362969, 2022). "In fact, IGF-1 is considered a key growth factor overproduced in asthma and obesity." (PMID 36160852, 2022). "Many systemic factors, dysregulated in obesity and T2D, may contribute to BC, including insulin, insulin-like growth factor 1 (IGF1), glucose, lipids, inflammatory cytokines, immune cells, steroids, the autonomic nervous system, adipokines and the microbiome." (PMID 36358839, 2022). "Finally, upregulation of the expression of certain microRNAs in muscle of humans with obesity impairs expression of muscle mitochondrial proteins, as well as that of muscle insulin-like growth factor-1 (IGF-1) that regulates protein anabolism in muscle." (PMID 35350688, 2022). "In a recent study conducted in an adult population, patients with higher levels of serum IGF1 and with a higher IGF1/IGFBP-3 ratio had a lower risk of NASH, while patients with obesity with/without MAFLD always had lower serum IGF1 levels." (PMID 36557260, 2022). "Whether liver-specific deletion of Igf1 in the context of obesity would alter disease outcome is unknown." (PMID 35741020, 2022). "Given the association of increased serum GHBP and IGF-1 levels with increasing BMI SDS in children, we assessed if AT cells might contribute to the increase in serum levels observed with overweight/obesity." (PMID 36384443, 2022). "Since AMPK activity is reduced in obesity, at least in human obese visceral fat, and IGF-1 may locally rise, obesity may oppose anoikis and promote metastasis." (PMID 36038791, 2022). "Therefore, we carried outa randomized trial to investigate the influences of circuit exercise training for12 weeks on cardiovascular risk factors, vascular inflammatory markers, andinsulin-like growth factor-1 (IGF-1) in elderly obesity women with sarcopenia." (PMID 39076242, 2022). "We aim to elucidate from a molecular and biochemical point of view if IGF1 in women with metabolic imbalances such as obesity or diabetes could be used in clinics as a novel, reliable estimator for the developmental competence of an oocyte." (PMID 35626647, 2022). "The protective effect of obesity on leukemic cells may be through increased levels of insulin and insulin-like growth factor-1 (IGF-1), which provides a chemoprotective niche and metabolic “fuel” to promote systemic inflammation." (PMID 35509847, 2022). "Moreover, the bioavailability of testosterone and estradiol is increased in obesity due to hyperinsulinemia and elevated IGF-1 activity, resulting in decreased hepatic production of SHBG." (PMID 36401194, 2022). "Interestingly, IGF1R, a receptor tyrosine kinase that mediates actions of insulin-like growth factor 1 and one of the factors that are altered in obesity is a key target of differentially expressed miRNAs identified by our framework including miR-182-5p." (PMID 35937842, 2022). "However, humans with obesity that also have lower levels of plasma IGF-1 have lower muscle protein synthesis compared to lean controls." (PMID 35350688, 2022). "Altered IGF-1 levels in obesity may be a consequence of an increased nutritional status and/or a general dysregulation involving various other hormones." (PMID 34386750, 2021).